C4B-AS1 (C4B antisense RNA 1)
Gene: Long non-coding RNA gene on chromosome 6 (32,032,713 to 32,036,258, reverse strand). Ensembl gene ENSG00000229776.
Homologues: Paralogues in human: C4A-AS1 (100% identical).